SLC4A4 (solute carrier family 4 member 4)
Diseases named in the same sentence as SLC4A4 in open-access papers (continued):
Sharing a sentence is not in itself a finding about the gene and the disease.
pancreatic adenocarcinoma (1 paper, 2023). "Inhibition of SLC4A4 in combination with immune checkpoint inhibitor treatment was applicable to overcome immunotherapy resistance and to prolong the survival of pancreatic adenocarcinoma bearing mice." (PMID 38102680, 2023). "which have experimentally proven that inhibition of the bicarbonate transporter SLC4A4 in pancreatic adenocarcinoma cells mitigated acidosis within the TME due to bicarbonate accumulation in the extracellular space." (PMID 38102680, 2023).
renal calculi (1 paper, 2025). "Her history of recurrent renal calculi since adolescence, progressive limb weakness, and eventual confirmation of SLC4A4 mutation illustrate the chronic and often under-recognized nature of hereditary RTA." (PMID 41377247, 2025).
retinitis pigmentosa (1 paper, 2017). Retinitis pigmentosa (RP) is an inherited retinal dystrophy leading to progressive loss of the photoreceptors and retinal pigment epithelium and resulting in blindness usually after several decades. "Slc4a4 has also been linked to retinitis pigmentosa (RP) type 17 and Elovl1 is an endogenous inhibitor of the visual cycle enzyme RPE65, defects in which cause RP type 2054–56." (PMID 29116131, 2017).
Splenomegaly (1 paper, 2022). Abnormal increased size of the spleen. "Extra-renal manifestations of Slc4a4 silencing in the mouse include growth retardation, ocular band keratopathy, splenomegaly, abnormal dentition and intestinal obstructions, most of which mimics the clinical findings observed in human patients." (PMID 35635440, 2022).
thyroid nodule (1 paper, 2018). A small circumscribed mass in the THYROID GLAND that can be of neoplastic growth or non-neoplastic abnormality. "In malignant thyroid nodules, a different expression of GALE has been reported, while SLC4A4 has been included in a 15-gene profile proposed as diagnostic biomarkers of thyroid tumour." (PMID 29304754, 2018).
Turner syndrome (1 paper, 2018). Turner syndrome is a chromosomal disorder associated with the complete or partial absence of an X chromosome. "The transcript of the SLC4A4 gene was almost undetectable, and the patient was also diagnosed with Turner’s syndrome." (PMID 29914390, 2018).
viral infection (1 paper, 2023). "Notably, a number of additional genes localized to SMARCA4-dependent genomic regions were those found to mediate viral infection in our CRISPR screen along with ACE2, such as SLC4A4 and HNF1A, thus suggesting that mSWI/SNF complexes regulate a coronavirus susceptibility gene expression axis." (PMID 36894709, 2023).
tumor (29 papers, 2014 to 2025). "SLC4A4 and other solute carrier family members have been found to be associated with tumorigenesis and tumor development." (PMID 35305629, 2022). "Among these the SLC4A4 gene was widely dysregulated in several tumor types when compared to pooled GTEx control group." (PMID 37397501, 2023). "Using previous single-cell sequencing data to visualize SLC4A4 expression in different cells revealed that SLC4A4 expression was significant in epithelial cells and barely expressed in other cells, including malignant tumor cells." (PMID 37152025, 2023). "The results showed a significantly decreased level of SLC4A4 expression in tumor samples compared to controls." (PMID 36468451, 2023). "On the other hand, SLC6A20, SLC5A1, SLC4A4, and SLC16A10 were positively associated with OS in 3 tumor types." (PMID 37397501, 2023). "Inhibiting SLC4A4 is considered a possible remedy to improve immunoreaction, which inhibits tumor growth and metabolic processes." (PMID 37894847, 2023). "Targeting SLC4A4 neutralises environmental pH and restores antitumour immunity, sensitising tumours to immune checkpoint blockade." (PMID 36807529, 2023). "DNA methylation analysis revealed that SLC4A4 CG probesets of the distal promoter region were hypomethylated (median beta value ≤0.2) in all Pan-Cancer tumor types." (PMID 37397501, 2023). "The reduced expression of SLC4A4 can promote cancer cell proliferation and migration traits in vitro or under the condition of immunodeficiency, which is mainly dependent on the tumor cell type." (PMID 37152025, 2023). "Our results showed that SLC4A4 gene expression was downregulated in the primary tumors, metastatic and recurrent tumor compared to solid tissue normal samples (p < 0.0001)." (PMID 36468451, 2023). "A reduction in tumour growth and metastasis to the lymph nodes and liver was observed in both models when Slc4a4 was deleted." (PMID 36807529, 2023). "In conclusion, SLC4A4 targeting leads simultaneously to the accumulation of bicarbonate and to the reduction of lactate in the tumor milieu." (PMID 36522548, 2022). "To dissect the effect of Slc4a4 depletion on metastatic growth independent from the effect on the primary tumor, we hydrodynamically injected KPC1 cells." (PMID 36522548, 2022). "In the subcutaneous setting with Panc02 tumors, anti-PD-1/anti-CTLA-4 treatment resulted in a synergic effect, with Slc4a4 deletion leading to tumor regression or to a static disease, overall offering an increased survival." (PMID 36522548, 2022). "In PDAC-bearing mice, genetic or pharmacological SLC4A4 targeting improves T cell-mediated immune response and breaches macrophage-mediated immunosuppression, thus inhibiting tumor growth and metastases." (PMID 36522548, 2022). "This suggests a potential role of SLC4A4 in tumor suppression, as well as in prognostic prediction in multiple malignancies, including CRC, thus representing a potential novel therapeutic CRC target." (PMID 35336739, 2022). "In accordance with the transcriptomic data, histological analysis showed that SLC4A4 expression was mostly restricted to the ductal cells within both the tumor and the adjacent pancreatic tissue." (PMID 36522548, 2022). "In this work, we explored the metabolic effects within the TME of Slc4a4 deletion in cancer cells and the impact of these modifications on tumor growth, anticancer immunity and response to immunotherapy in mouse models of PDAC." (PMID 36522548, 2022). "We confirmed the same reduction in tumor growth with a second gRNA directed against Slc4a4, ruling out any (rare) off-target effect of the gRNA." (PMID 36522548, 2022). "Overall, these data show that inhibition of SLC4A4 in combination with ICB strongly reduces tumor growth and cancer aggressiveness, paving the way toward a possible therapeutic strategy to overcome PDAC resistance to immunotherapy." (PMID 36522548, 2022).
tumor (continued). "The major role of CD8+ T cell activation after Slc4a4 targeting was further supported by the observation that CD8+ T cell depletion completely abolished the difference in tumor growth in the subcutaneous Panc02 and orthotopic KPC1 and KPC3 models." (PMID 36522548, 2022). "SLC4A4 acts as a tumor promotor that accelerates tumor growth, inhibits apoptosis and arrests cell cycle progression among PCa by regulating key elements of the AKT pathway." (PMID 35305629, 2022). "When engineered KPC cells (hereafter referred to as KPC1) were injected orthotopically in the pancreas, the effects of Slc4a4 depletion were even more pronounced, with a reduction in tumor growth of almost 90%." (PMID 36522548, 2022). "In a second KPC clone (KPC2), despite a milder ablation of the targeted protein, Slc4a4 depletion led to an ~50% reduction in tumor growth and metastatic mesenteric lymph nodes." (PMID 36522548, 2022). "Western blotting was used to determine the possible association between SLC34A2 and SLC4A4 protein expression with the p-ERK, p-JNK, and p-P38 protein expression in tumor tissues when compared to the adjacent normal thyroid tissue." (PMID 34405007, 2021). "RT-PCR results showed that expression of SLC34A2 mRNA was drastically up-regulated while SLC4A4 mRNA was drastically down-regulated in tumor tissue, when compared with the adjacent normal thyroid tissue (P all < 0.05)." (PMID 34405007, 2021). "SLC4A4 mRNA expression depends exclusively on hypoxia inducible factor 1 subunit alpha, a tumor suppressor gene in ccRCC." (PMID 30668544, 2019). "SLC4A4 may be involved in tumor suppression and prognostic prediction for several cancers, including CRC." (PMID 39852182, 2025). "The results of marginal model analysis with the Generalized Estimating Equations (GEE) approach indicated that the expression level of SLC4A4 in the tumor tissues is reduced compared to the healthy tissues (Model 1: b = −0.28, p‐value <0.001 and Model 2: b = −0.34, p‐value <0.001)." (PMID 36468451, 2023). "The correlation analysis between DNA methylation levels of CG probesets and gene expression of the SLC4A4 gene revealed that correlation pairs were mainly observed in the body CG probesets showing a positive correlation in several tumor types (N = 18 for cg15621697)." (PMID 37397501, 2023). "Inhibition of SLC4A4 activity can increase the accumulation of bicarbonate in the extracellular space and reduce the secretion of lactate, thereby alleviating acidosis in the acidic tumor microenvironment." (PMID 37894847, 2023). "The immunohistochemical results highlighted the decreased SLC4A4 expression in the tumor." (PMID 37152025, 2023). "By targeting SLC4A4, antitumour immunity is restored, and tumours are sensitised to immunotherapy." (PMID 36807529, 2023). "Also, overexpression of SLC4A4 in tumor specimens correlated with disease progression via the AKT‐mediated signaling pathway." (PMID 36468451, 2023). "More importantly, SLC4A4 expression in the N1–N2 group was much lower than that in N0, suggesting that SLC4A4 might also mediate tumor cell metastasis to lymph nodes." (PMID 37152025, 2023). "Our current study verified that SLC4A4 expression was dramatically higher in PCa clinical tissues and cell lines than normal prostate tissues and cells, and increased along with the malignant degree of the tumor." (PMID 35305629, 2022). "Based on these results, we speculated that the combination of Slc4a4 targeting and immunotherapy could further tackle tumor progression." (PMID 36522548, 2022). "SLC4A4 acts as a tumor promotor in PCa by regulating key components of the AKT pathway and may therefore act as a potential therapeutic target for PCa treatment." (PMID 35305629, 2022). "Moreover, when Panc02 cancer cells were injected orthotopically into the pancreas, Slc4a4 targeting led to a reduction of both tumor weight and number of metastatic mesenteric lymph nodes." (PMID 36522548, 2022).
tumor (continued). "Despite this, in subcutaneous Panc02 tumors, Slc4a4 targeting strongly reduced tumor growth." (PMID 36522548, 2022). "The prevalent expression of SLC4A4 in tumor epithelial cells suggests that the inhibition of this transporter might predominantly affect cancer cells and have modest direct effects on other cell types of the TME." (PMID 36522548, 2022). "High expression of SLC4A4 in tumor specimens was significantly correlated with disease progression." (PMID 35305629, 2022). "In the orthotopic KPC1 model where Slc4a4 targeting per se already displayed a strong reduction in tumor growth, we could observe a trend in tumor growth reduction by adding the treatment with anti-PD-1 and anti-CTLA-4 together." (PMID 36522548, 2022). "Also with this ‘colder’ KPC clone, Slc4a4 targeting led to a reduction in tumor growth and metastatic mesenteric lymph nodes." (PMID 36522548, 2022). "Unfortunately, we didn't find the correlation between SLC4A4 expression with the Age, Gender, Pathology, Tumor size, T stage, N stage, M stage of CRC patients, it might due to the limit of sample number in the current study." (PMID 32284764, 2020). "Moreover, the inhibition of the Na+/HCO3- cotransporter SLC4A4 has been recently demonstrated to attenuate the acidic pHe by accumulating extracellular NaHCO3 and reduce in vivo tumor growth and metastasis while restoring antitumor immunity and increasing response to immunotherapy." (PMID 37445810, 2023). "SLC4A4 could be an oncogene to predict tumour malignancy and survival in PCa patients." (PMID 35305629, 2022). "Thus, SLC4A4 may suppress tumor by stimulating immune system, and, as a result, more immune cells in tumor microenvironment were activated to fight the cancer." (PMID 35655081, 2022). "Specifically, miRNA-222 downregulates tumor suppressor genes such as PTEN, p27 and p57, and SLC4A4, resulting in uncontrolled cell proliferation and survival and contributing to tumor growth and multifocality." (PMID 39125979, 2024). "Of these, SLC4A4 was the most highly expressed in PDAC epithelial cells, according to their analysis of single‐cell RNA‐seq data from human PDAC tumours." (PMID 36807529, 2023). "This suggested that the combination of SLC4A4 and ICB targeted therapy can still have value in more aggressive and less immunogenic tumours." (PMID 36807529, 2023). "Based on this study, we confirmed the downregulation of SLC4A4 expression and upregulation of hsa‐miR‐223‐3p and hsa‐miR‐106a‐5p, which may be regarded as a regulatory network in CRC tumor samples." (PMID 36468451, 2023). "Necropsy did not reveal any sign of tumor nor the presence of metastatic mesenteric lymph nodes, indicating a complete tumor regression and a synergic effect between Slc4a4 deletion and ICB treatment." (PMID 36522548, 2022). "Due to the significantly decrease of SLC4A4 levels in CRC tissues and its role in CRC remained largely unknown in most of tumors including CRC, and therefore were selected as a candidate tumor suppressor gene." (PMID 32284764, 2020). "The results revealed that expression levels of SLCO4C1, POU4F1, DNASE1L2, WDR72, LPO, and C7 in tumor tissues were significantly higher than those in normal tissues, while the expression differences of SLC4A4, CELF4, and SLC11A1 were not statistically significant." (PMID 37745305, 2023). "Interestingly, the authors showed that SLC4A4 is not actually upregulated in tumour cells compared with normal pancreatic epithelium." (PMID 36807529, 2023). "Therefore, it can be hypothesized that the MAPK signaling pathway might act as a pivotal downstream (rather than upstream) signaling pathway for SLC34A2 and SLC4A4, to promote the tumor progression of PTCs." (PMID 34405007, 2021). "The relative expression of SLC4A4 in log2 (FPKM+1) form ranged from 4.85 to 10.62 units in normal tissues and from 3.59 to 10.92 units in tumor tissues." (PMID 30668544, 2019).
tumor (continued). "However, in the immune cold KPC3 model, Slc4a4 deletion still sensitised the tumours to ICB and reduced tumour growth even though no regression was observed." (PMID 36807529, 2023).
cancer (18 papers, 2016 to 2025). A tumor composed of atypical neoplastic, often pleomorphic cells that invade other tissues. "Further, the SLC4A4 expression level in cancer tissues was significantly associated with the degree of disease progression." (PMID 36618366, 2022). "Thus, SLC4A4 is involved in the suppression of tumorigenesis and the development of cancer and has important diagnostic and therapeutic implications." (PMID 36468451, 2023). "As a bicarbonate transporter, SLC4A4 contributes to maintaining pH balance, which is vital for cancer cell survival, and impacts the acidic environment that typically suppresses immune cell activity and promotes immune evasion." (PMID 39852182, 2025). "Accumulating evidence showed that the expression of SLC4A4 is different in a variety of malignant tumors." (PMID 35305629, 2022). "Despite that pH is often assumed but not always measured in vivo, in this study, we were able to confirm our in vitro findings and show that Slc4a4 targeting in cancer cells importantly affects the TME acidity using MRS technology." (PMID 36522548, 2022). "Aiming to a rewiring of the TME, at least in PDAC, SLC4A4-targeted strategies offer the advantage to tackle bicarbonate transport in cancer cells only and to open a therapeutic window in which ICB can exert their effects." (PMID 36522548, 2022). "MicroRNA 223-3p inhibited the expression of SLC4A4 in clear cell renal cell carcinoma, promoting the cancer proliferation and metastasis." (PMID 35305629, 2022). "On the contrary, it is likely that SLC4A4-proficient cancer cells are able to preserve an optimal pHi by sustaining bicarbonate import and thus preventing acidosis-dependent glycolysis inhibition." (PMID 36522548, 2022). "Functionally, SLC4A4 inhibition in PDAC cancer cells mitigates the acidosis of the TME due to bicarbonate accumulation in the extracellular space and a decrease in lactate production by cancer cells as the result of reduced glycolysis." (PMID 36522548, 2022). "Expression of Lamp2 was decreased in both Panc02 and KPC1 sgSlc4a4 tumors compared to the sgNT controls, supporting our conclusion that Slc4a4 depletion in cancer cells is sufficient to mitigate the acidic pH of the TME in PDAC." (PMID 36522548, 2022). "Based on the well-documented interplay between pH and immune response, and the absence of an antitumor effect of Slc4a4 inhibition in immunodeficient mice, we studied the immune landscape after SLC4A4 depletion in cancer cells." (PMID 36522548, 2022). "Therefore, crucially, targeting Slc4a4 can not only increase pHe via reducing bicarbonate import, but also via decreasing cancer cell lactate production, thus targeting both aspects of TME acidity that impair anticancer immunity." (PMID 36807529, 2023). "Similarly, staining for SLC4A4 in mice displayed a positive signal in the cancer cell compartment of orthotopic KPC tumors (obtained from the KrasG12D; p53LSL.R172H; P48:Cre transgenic mouse model) and in ducts and ductules of the surrounding pancreatic tissue." (PMID 36522548, 2022). "Similarly, miR-223-3p, highly expressed in cancer renal tissue and positively correlated with ccRCC staging and progression, downregulates at protein level the solute carrier family 4, member 4 (SLC4A4), which also regulates KRAS, therefore favoring proliferation and metastasis." (PMID 34440329, 2021). "For instance, Destruction of SLC4A4 or SLC4A9 by genetic or pharmacological methods have been reported to acidify intracellular pH and suppress cancer cell growth." (PMID 35305629, 2022). "To discriminate cell-autonomous from non-cell-autonomous effects of SLC4A4 modulation in cancer cells, we orthotopically injected either Panc02 or KPC1 cells in immunodeficient nude mice." (PMID 36522548, 2022). "Among the four groups of acid-extruding transporter genes, SLC4A4/9 are down-regulated or show no changes in their expressions across all cancer types except for PRAD with SLC4A4 being up-regulated." (PMID 31071451, 2019).
infection (4 papers, 2018 to 2025). The state of being infected such as from the introduction of a foreign agent such as serum, vaccine, antigenic substance or organism. "There was an overall decreased ion transport activity during infection (albeit more so in susceptible mice due to loss of intestinal differentiation) as exemplified by the reduced expression levels of the solute carriers Slc4a4 and Slc9a2 in both susceptible and resistant congenic mice." (PMID 29339782, 2018). "Furthermore, results of western blotting also indicated that the expression of SLC4A4 protein was distinctly down-regulated after infection in comparison with shCtrl cells." (PMID 35305629, 2022). "Cell growth and differentiation (HRASLS2), transport (PNN, SLC4A4, and HBA1), metabolism (SRD5A3), and immune response (SSC4D) involved genes were highly regulated in the early HEV gt3 infection." (PMID 32877413, 2020).
brain disorder (1 paper, 2024). A disease affecting the brain or part of the brain. "While NHE1 is an H+ extrusion in astrocytes regardless of the extracellular pH or ion concentration, Slc4a4 transports sodium/bicarbonate bidirectionally across the cell membrane depending on the electrogenic gradients, making it a versatile “modulator” for drug targeting in brain disorders." (PMID 38709635, 2024).